FOXM1 (forkhead box M1)
Diseases named in the same sentence as FOXM1 in open-access papers (continued):
Sharing a sentence is not in itself a finding about the gene and the disease.
malignant peripheral nerve sheath tumor (4 papers, 2015 to 2025). Malignant peripheral nerve sheath tumor (MPNST) is a rare and often aggressive soft tissue sarcoma occurring in a wide range of anatomical sites. "Transcriptional activator Foxm1 is involved in DNA replication and cell proliferation and is frequently highly expressed in tumor, including malignant peripheral nerve sheath tumor." (PMID 37922116, 2023).
mucinous adenocarcinoma (4 papers, 2017 to 2024). An invasive adenocarcinoma composed of malignant glandular cells which contain intracytoplasmic mucin. "Inhibition of FOXM1 in human mucinous adenocarcinoma cells inhibited mucinous characteristics and reduced tumor invasion in an orthotopic xenograft mouse model." (PMID 29267283, 2017). "Adenocarcinomas in FOXM1 transgenic mice expressed increased MUC5B and MUC5AC, and reduced NKX2.1, which are characteristics of mucinous adenocarcinomas." (PMID 29267283, 2017).
oesophageal cancer (4 papers, 2019 to 2024). "In this study, we investigated the abundance of each FOXM1 isoform in oesophageal cancer cells and found that FOXM1c was the predominant isoform." (PMID 30485581, 2019). "Before identifying the abundancy of each FOXM1 isoform in oesophageal cancer, we employed four ESCC cell lines to detect the expression levels of whole FOXM1 by Western blot." (PMID 30485581, 2019). "In the present study, we found that the FOXM1c isoform dominated among the four FOXM1 isoforms in oesophageal cancer cells." (PMID 30485581, 2019). "In summary, we determined that FOXM1c was the predominant isoform among the four isoforms of FOXM1 in oesophageal cancer." (PMID 30485581, 2019). "Although FOXM1 was highly expressed in oesophageal cancer and correlated with poor prognosis, the major isoform involved remains unknown." (PMID 30485581, 2019). "A previous study revealed that miR‐204, by targeting FOXM1, could act to suppress cell invasion in oesophageal cancer, which was in consistency with the findings of our study." (PMID 31389660, 2019).
rhabdomyosarcoma (4 papers, 2016 to 2023). A rare aggressive malignant mesenchymal neoplasm arising from skeletal muscle. "A FoxM1/Bub1b signaling pathway is an identified required component for survival and growth of rhabdomyosarcoma." (PMID 27074562, 2016). "Finally, FOXM1 is important in rhabdomyosarcoma wherein it directly binds to the Bub1b promoter, which has a FOXM1 consensus-binding site." (PMID 27074562, 2016). "Targeting FOXM1 may prove a useful future therapeutic strategy in rhabdomyosarcoma." (PMID 27074562, 2016).
synovial sarcoma (4 papers, 2016 to 2024). "The role of FOXM1 in synovial sarcoma needs experimental evaluation." (PMID 27074562, 2016). "However, inferring its effect on upregulating pluripotency genes and in particular activation of SOX2 in other tumors raises an important question: Does inhibition of FOXM1 vicariously targets SOX2 in synovial sarcoma?" (PMID 27074562, 2016). "Furthermore FOXM1 participates in epithelial to mesenchymal transition, a determinant of the morphological subtypes of synovial sarcoma." (PMID 27074562, 2016). "In Synovial Sarcoma (SS), characterized by the fusion of the SS18 gene to either SSX1, SSX2, or SSX4, the expression of FOXM1 associates with poor prognosis and correlates with cell-cycle genes." (PMID 38946804, 2024).
acute kidney injury (3 papers, 2021 to 2024). Sudden and sustained deterioration of the kidney function characterized by decreased glomerular filtration rate, increased serum creatinine or oliguria. "Acute kidney injury (AKI) strongly upregulates the transcription factor Foxm1 in the proximal tubule in vivo, and Foxm1 drives epithelial proliferation in vitro." (PMID 38916959, 2024). "After acute kidney injury, upregulation of FoxM1 in the proximal tubule drives epithelial proliferation through the activation of the atypical cyclin-dependent kinase cyclin F." (PMID 38916959, 2024).
bladder urothelial carcinomas (3 papers, 2017 to 2024). "Previous study has established that LRPPRC is often upregulated in urothelial carcinoma of the bladder, where it regulates redox balance via the circANKHD1/FOXM1 pathway to drive tumorigenesis." (PMID 39445012, 2024). "In the present study the prognostic value of FOXM1 has been evaluated for the first time in urothelial bladder cancer." (PMID 28498805, 2017).
breast adenocarcinoma (3 papers, 2020 to 2024). "Notably, CENPA, FOXM1, and MYBL2 are also key regulators of cancer-specific enhancers in breast adenocarcinoma of the basal subtype, but they are associated with distinct sets of activated enhancers." (PMID 32925947, 2020). "In previous analyses, we found that FOXM1 and MYBL2 were activated in breast adenocarcinoma (BRCA)." (PMID 32925947, 2020).
colitis (3 papers, 2015 to 2024). Inflammation of the colon. "In a colorectal inflammatory tumor model, AhR knockdown in intestinal epithelial cells increases basal stem cell and crypt injury-induced cell proliferation by upregulating forkhead box M1 (FoxM1) signaling and promotes colitis-associated carcinogenesis." (PMID 36672697, 2023). "In line with findings from tumor samples, FOXM1 expression was found to be enriched in colitis samples as well, suggesting its pivotal role in driving malignant proliferation of tumor cells." (PMID 39542983, 2024).
diffuse large B-cell lymphoma (3 papers, 2018 to 2021). "FOXM1, a pivotal cell cycle regulator, is overexpressed due to Sonic Hedgehog (Shh) signaling activation in basal-like breast cancer (BLBC), diffuse large B-cell lymphoma (DLBCL), and pancreatic cancer." (PMID 33717680, 2021). "Applying the Bonferroni correction method to identify false positive results, the significance of FOXM1 and UBE2C expression correlation is maintained in all tumors analysed, except for lymphoid neoplasm diffuse large B-cell lymphoma." (PMID 29596365, 2018).
gestational diabetes (3 papers, 2011 to 2025). Carbohydrate intolerance first diagnosed during pregnancy. "Additionally, FOXM1’s involvement extends to nutrition-induced β cell growth and gestational diabetes, highlighting its importance in β cell function in various physiological conditions." (PMID 39846251, 2025).
ischemia (3 papers, 2019 to 2025). A hypoperfusion of the BLOOD through an organ or tissue caused by a PATHOLOGIC CONSTRICTION or obstruction of its BLOOD VESSELS, or an absence of BLOOD CIRCULATION. "In a recent study, Piret and Mallipattu, (2020) found that in mice with unilateral ischemia–reperfusion kidney injury, Foxm1 was vigorously upregulated after 2 days and returned to baseline levels after 14 days." (PMID 36246123, 2022). "To determine the expression of FoxM1 in intestinal mucosa regeneration after I/R injury, we tested the expression of FoxM1 in intestinal tissues that underwent 1 h of ischemia followed by 3, 6, 12, or 24 h of reperfusion." (PMID 31704909, 2019). "The intrinsic mechanism of FoxM1 activity in the mucosa after intestinal ischemia/reperfusion (I/R) injury has not been reported." (PMID 31704909, 2019).
metastatic carcinoma (3 papers, 2021 to 2024). A carcinoma which has spread from the original site of growth to another anatomic site. "Further immunohistochemistry analysis of the lung metastatic cancers detected a reduction in both integrin b1 and FoxM1 levels in the S02 treatment groups." (PMID 37398311, 2023). "One possible explanation could be that MYBL2 and FOXM1 might influence cancer cell survival through mechanisms other than cell cycle regulation, such as apoptosis or metabolic adaptation, which are critical for sustaining the growth and survival of metastatic cancer cells." (PMID 39518122, 2024).
myeloid leukemia (3 papers, 2018 to 2022). A clonal proliferation of myeloid cells and their precursors in the bone marrow, peripheral blood, and spleen. "In the K562 human immortalized myelogenous leukemia cell line, FOXM1 enrichment was noted on the promoter region with a peak signal of ≈167 bp upstream of the CD274 transcription start site." (PMID 35975458, 2022). "Determination of the role of TRPM2 in doxorubicin sensitivity of the myeloid leukemia cell line U937 similarly demonstrated reduced FOXM1, E2F1, and expression of proteins involved in cell cycle and DNA damage response in cells with TRPM2 deletion." (PMID 35428820, 2022).
myeloid neoplasm (3 papers, 2018 to 2023). Proliferation of myeloid cells originating from a primitive stem cell. "We studied FOXM1 mRNA expression levels in BM-MSC isolated from patients with myeloid neoplasms as compared to healthy donors." (PMID 36481766, 2022). "Having established the role of FOXM1 in mediating chemotherapy resistance in myeloid neoplasms, we went on to inhibit this transcription factor." (PMID 30089730, 2018). "Our findings demonstrate that precise regulation of Foxm1 expression is crucial for normal HSC function and both upregulation and downregulation of Foxm1 can contribute to the pathogenesis of myeloid malignancies through distinct cellular and molecular mechanisms." (PMID 37526082, 2023). "In conclusion, the present study demonstrates that impairment of FOXM1 expression in MSC isolated from de novo and therapy-related myeloid neoplasms may underlie their defective capacity to support normal hematopoiesis." (PMID 36481766, 2022). "Transgenic overexpression of FOXM1 confers chemotherapy resistance in myeloid neoplasms." (PMID 30089730, 2018). "In order to further prove a potential role for FOXM1 in AML chemoresistance, we induced an FLT3-ITD–driven myeloid neoplasm in a FOXM1-overexpressing transgenic mouse model and demonstrated significantly higher residual disease after standard chemotherapy." (PMID 30089730, 2018). "The function of the FOXM1 gene has not been examined in myeloid neoplasms." (PMID 36481766, 2022).
non-Hodgkin lymphoma (3 papers, 2015 to 2024). Distinct from Hodgkin lymphoma both morphologically and biologically, non-Hodgkin lymphoma (NHL) is characterized by the absence of Reed-Sternberg cells, can occur at any age, and usually presents as a localized or generalized lymphadenopathy associated with fever and weight loss. "Tumors in which FOXM1 is implicated have a temporal incidence consistent with this biology, such as anaplastic large cell lymphoma being the most common childhood form of non-Hodgkin's lymphoma." (PMID 27074562, 2016). "This locus is amplified in several types of cancer with FOXM1 amplification among the most prevalent molecular aberration in non-Hodgkin's lymphoma." (PMID 27074562, 2016). "Amplification of the FOXM1 gene is increased in TNBC (33.3%) /basal-type BCs and three subtypes of non-Hodgkin lymphoma." (PMID 39594778, 2024).
pancreatic adenocarcinoma (3 papers, 2020 to 2023). "Through GEPIA, FOXM1 exerted a higher expression in pancreatic adenocarcinoma (PAAD), and corresponded with a poor prognosis." (PMID 36292640, 2022).
prostate adenocarcinoma (3 papers, 2009 to 2021). "Increased expression of Foxm1 was found in human prostate adenocarcinomas and was correlated with the severity of the disease." (PMID 25254494, 2014).
testicular germ cell tumor (3 papers, 2019 to 2022). A germ cell tumor arising from the testis. "A better understanding of FOXM1 function and regulation could lead to novel treatment strategies for a broad range of cancers, including germ cell tumors." (PMID 35743036, 2022). "Notably, amongst all tumor types with TCGA data, FOXM1 was most frequently amplified in testicular germ cell tumors (TGCT), which is also the cancer type showing the highest level of FOXM1 mRNA and protein expression." (PMID 30795624, 2019). "For example, TGCT (i.e., testicular germ cell tumors) showed the highest FOXM1 expression level and FOXM1 amplification frequency among TCGA cancer types." (PMID 30795624, 2019).
anaplastic astrocytoma (2 papers, 2009 to 2015). "To verify these observations at the protein level, we determined FoxM1 expression using a tissue microarray (TMA) constructed in our laboratory, which harbors 13 astrocytomas (grade II), 25 anaplastic astrocytomas (grade III) and 80 GBM (grade IV) specimens." (PMID 26444992, 2015).
anaplastic large cell lymphoma (2 papers, 2016 to 2019). Anaplastic large cell lymphoma (ALCL) is a rare and aggressive peripheral T-cell non-Hodgkin lymphoma, belonging to the group of CD30-positive lymphoproliferative disorders, which affects lymph nodes and extranodal sites. "In this study, we examined the significance of FOXM1 in NPM-ALK-positive anaplastic large cell lymphoma (NPM-ALK + ALCL), with a focus on how it interacts with NPM-ALK, which is a key oncogenic driver in these tumors." (PMID 31390744, 2019). "FOXM1 protein is stabilized in anaplastic large cell lymphoma by direct interaction with nucleophosmin (NPM)." (PMID 27074562, 2016).
anaplastic thyroid carcinoma (2 papers, 2017 to 2019). "In thyroid tumors, it has been reported that FOXM1 promotes the pathogenesis of PTC and the invasive phenotype of anaplastic thyroid carcinoma." (PMID 28187428, 2017).
B-cell lymphoma (2 papers, 2016 to 2021). "Both Plk1 and Foxm1 are promising therapeutic targets in B-cell lymphoma." (PMID 34363012, 2021).
brain cancer (2 papers, 2024 to 2025). A primary or metastatic malignant neoplasm affecting the brain. "For example, miR-128 plays a crucial role in nervous system development by targeting Forkhead Box M1, cAMP response element-binding protein (CREB), splicing factor SC35, and LIM domain kinase 1 (Limk1), and has also been linked to various types of brain cancer via targeting STAT5B and KRAS genes." (PMID 40563979, 2025). "Recent research has underscored the essential role of FOXM1 oncogenic signaling in driving tumorigenesis and the progression of aggressive solid cancers such as TNBC, pancreatic, lung, and brain cancers." (PMID 39594778, 2024).
carcinoid (2 papers, 2017 to 2019). "Distinguishing LCNECs from SCLCs with the combination of FOXM1(+)/p27kip1(high) and discriminating atypical carcinoids from typical carcinoids with the combination of FOXM1(−)/p21waf1/cip1(−) have the best sensitivity." (PMID 30992007, 2019). "FOXM1 is expressed more frequently in high-grade pulmonary neuroendocrine tumors than in carcinoid tumors." (PMID 30992007, 2019). "In our study, immunohistochemistry in 151 cases of ratified BP-NETs demonstrated that FOXM1 as single marker was strongly upregulated in SCLC samples compared to the better-differentiated carcinoid tumors controls." (PMID 29228593, 2017). "Concerning cytosolic localization, we found that 69.9% (86/123) of the SCLC samples were positive, whereas 96.4% (27/28) of carcinoid samples were immunoreactive for inactive FOXM1 in the cytoplasm (p=0.004)." (PMID 29228593, 2017). "High immunoreactivity for nuclear FOXM1 was detected in 47.3% (58/123) of the SCLC samples, whereas only 29.4% (5/17) of the atypical carcinoid (ATC) samples and 9.1% (1/11) of the typical carcinoid (TC) samples were positively stained for nuclear FOXM1." (PMID 29228593, 2017).
cardiac ischemia (2 papers, 2025). "Here, by conducting a comprehensive analysis of cardiac samples obtained from clinical ICM patients and mice subjected to I/R injury, we uncovered a significant correlation between the expression of Foxm1 and the pathogenesis of myocardial ischemia." (PMID 40546121, 2025). "In rats models of myocardial ischemia-reperfusion, forced FOXM1 expression reduced apoptosis and infarct size." (PMID 41004495, 2025). "Conversely, FOXM1 overexpression preserves mitochondrial bioenergetics and confers protection against cardiac ischemia–reperfusion injury in both murine and porcine models." (PMID 40546121, 2025).
cardiomyopathy (2 papers, 2025). A disease of the heart muscle or myocardium proper. "Future studies employing comprehensive time-course CIH models with additional intermediate stages are needed to fully delineate the dynamic changes in myocardial FOXM1 during the development of OSA-associated cardiomyopathy." (PMID 41004495, 2025). "The downregulation of miR-320b in OSA-exo and the upregulation of FOXM1 in OSA-exo-treated cardiomyocytes implicated a miR-320b-FOXM1 axis in OSA-associated cardiomyopathy." (PMID 41004495, 2025). "The results suggested that the downregulation of exosomal miR-320b in OSA patients may serve as a compensatory mechanism to protect against early OSA-associated cardiomyopathy by upregulating FOXM1." (PMID 41004495, 2025). "Given that FOXM1 is a crucial regulator of cardiomyocyte proliferation and their regeneration after injury, we speculated that miR-320b might play a role in OSA-associated cardiomyopathy by targeting FOXM1." (PMID 41004495, 2025).
Cirrhosis (2 papers, 2018 to 2019). A chronic disorder of the liver in which liver tissue becomes scarred and is partially replaced by regenerative nodules and fibrotic tissue resulting in loss of liver function. "In addition to triggering the malignant transformation of liver cells during the progression of chronic hepatitis to cirrhosis, hepatitis B virus may also cause genetic recombination and the activation of oncogenes such as ‘forkhead box protein M1’ (FOXM1)." (PMID 31877715, 2019).
colorectal adenocarcinoma (2 papers, 2017 to 2018). The most common type of colorectal carcinoma. "Notably, the inmunodetection of FOXM1 in the nuclei of tumor cells in human colorectal adenocarcinomas was significantly associated with response of patients to cetuximab." (PMID 28423516, 2017).
COVID-19 (2 papers, 2022 to 2023). A disease caused by infection with severe acute respiratory syndrome coronavirus 2. "Moreover, FOXM1-dependent tissue regeneration is impaired in severe COVID-19 cases, causing sustained lung injury and a high fatality rate." (PMID 35625619, 2022). "It has also been found that FOXM1 was highly expressed in the lungs of COVID-19 patients, which also suggests that co-expression of FOXM1 with CENPE may have an important impact on the regulatory process of viral replication and spread." (PMID 37335738, 2023).
diabetic foot ulcer (2 papers, 2024 to 2025). "Forkhead box M1 (FOXM1) TF has been shown to promote wound healing in diabetic foot ulcers by enhanced M2 polarization involving SEMA3C/NRP2/Hedgehog signaling." (PMID 39585119, 2024). "In a study on diabetic foot ulcer (DFU), it was also found that the mediator of macrophage and neutrophil recruitment is FOXM1, which is responsible for the activation and recruitment of inflammatory cells and has the function of activating and promoting the survival of immune cells." (PMID 40566633, 2025).
diabetic kidney disease (2 papers, 2023 to 2025). Progressive kidney disorder caused by vascular damage to the glomerular capillaries, in patients with diabetes mellitus. "The expression of FOXM1 in the renal tissues of patients with diabetic nephropathy was low." (PMID 37238726, 2023). "In summary, FOXM1 inhibits the NF-κB signaling pathway through the transcriptional activation of SIRT4, which inhibits the NLRP3 inflammasome and prevents kidney injury and podocyte death in diabetic nephropathy patients." (PMID 37238726, 2023).
dysplasia (2 papers, 2009 to 2023). A usually neoplastic transformation of the cell, associated with altered architectural tissue patterns. "It is important to emphasise that our data showed that FOXM1 gene is significantly upregulated in genomically unstable oral premalignant (dysplasia and erythroplakia) and HNSCC samples." (PMID 19287496, 2009). "Foxm1-haploinsufficient mice developed hematopoietic dysplasia under long-term chronic stress." (PMID 37526082, 2023).
embryonal carcinoma (2 papers, 2013 to 2016). A non-seminomatous malignant germ cell tumor characterized by the presence of large germ cells with abundant cytoplasm resembling epithelial cells, geographic necrosis, high mitotic activity, and pseudoglandular and pseudopapillary structures formation. "Retinoic acid induced differentiation of human NT2/D1 embryonic carcinoma cells decreases expression of FOXM1." (PMID 27074562, 2016).